HDAC1 (histone deacetylase 1)
Diseases named in the same sentence as HDAC1 in open-access papers (continued):
Sharing a sentence is not in itself a finding about the gene and the disease.
breast tumors (13 papers, 2006 to 2024). "A meta-analysis evaluating seven papers reporting on the HDAC1 expression in breast tumors in women found that the higher expression of this enzyme is associated with favorable prognostic factors and better overall survival times." (PMID 38028583, 2023). "Previous studies have shown that HDACs are overexpressed in ER-α positive breast tumors, and HDAC1, HDAC3 and HDAC6 protein expressions correlate with ER-α expression." (PMID 30352569, 2018). "We show for the first time that a concomitant high expression of MBP-1 and HDAC1 inversely correlates with ERBB2 expression in primary breast tumors." (PMID 23421821, 2013). "Together these results inferred that the interaction and coordinated activity between TBX2 and CoREST proteins LSD1, ZNF217 and HDAC1 may be essential for repression of TSGs to promote breast tumour survival." (PMID 35687133, 2022). "Here, we demonstrate a previously unknown mechanism of TBX2-mediated gene repression in breast tumours, whereby TBX2 physically interacts with CoREST-associated proteins LSD1, HDAC1 and the ZNF217 oncogene." (PMID 35687133, 2022). "We also report a significant inverse correlation between ERBB2 expression and both MBP-1 (r= −0.278, p= 0.031) and HDAC1 (r= −0.267, p= 0.037) protein levels in primary breast tumors, and, accordingly, we propose MBP-1/HDAC1/ERBB2 relative expression as a diagnostic marker in breast IDC." (PMID 23421821, 2013). "HDAC1 was analysed by SSCP, and a silent polymorphism was identified in one breast tumour sample." (PMID 16638127, 2006). "Explicitly, genomic profiling of these epigenetic enzymes displayed increases in HDAC1, 2, 8, 10, 11, and Sirtuins (SIRTs) 6 and 7, and decreases in HDAC4-7, -9, and SIRT1-4 levels, respectively, in TCGA breast tumors." (PMID 38003678, 2023). "Breast cell lines showed downregulation of HDAC1, HDAC2, HDAC5, EZH2, EP300, and PCAF compared to breast tumours." (PMID 16638127, 2006). "We further found that mRNAs of SAP30, HDAC1, RBBP4, and RBBP7 but not other core subunits were significantly induced in all 4 major subtypes of breast tumors." (PMID 37655663, 2023). "SIN3B, HDAC1, HDAC2, SUDS3, and RBBP4, but not SIN3A and SAP18, were also upregulated to a lesser degree in human breast tumors." (PMID 37655663, 2023).
cardiac hypertrophy (13 papers, 2013 to 2025). "HDAC1 and HDAC2 regulate cardiac hypertrophy in a similar manner, and HDAC1 deficiency induces HDAC2 expression in embryonic stem cells." (PMID 23835259, 2013). "Curcumin demonstrates remarkable cardioprotection by inhibiting p300 histone acetyltransferase (HAT) activity, preventing pathological cardiac hypertrophy, and modulating histone deacetylase 1 (HDAC1) expression to improve vascular structure." (PMID 40428388, 2025). "Numerous studies have confirmed that class II HDACs (HDAC4, 5, 7, 9, 10) inhibit the development of myocardial hypertrophy, while class I HDACs (HDAC1, 2, 3, 8) have a positive effect on myocardial hypertrophy." (PMID 38584203, 2024). "Because histone deacetylase 1 (HDAC1) inhibition lowers pathological cardiac hypertrophy and oxidative stress, we assessed the exosomal level of maspin, an HDAC1 inhibitor delivered by exosomes." (PMID 37161563, 2023). "Cardiac specific loss of HDAC1 and HDAC2 for example results in cardiac arrhythmias and heart failure, while loss of HDAC3 function leads to cardiac hypertrophy." (PMID 23341106, 2013). "O-GlcNAc directly mediates the expression of fetal genes in response to hypertrophic stimuli, and O-GlcNAc modifies mSin3A and HDAC1, which regulate cardiac hypertrophy." (PMID 23835259, 2013). "Both Camk2d and Hdac1 are previously reported to regulate cardiac hypertrophy." (PMID 38533084, 2024). "In contrast to the epithelial nuclear HDAC1/2 oxidation, NOX4-dependent oxidation promoted nuclear exit of HDAC4 in mouse heart, while mice with NOX4 deficiency in cardiac myocytes were protected against pressure-overload-induced cardiac hypertrophy." (PMID 33802941, 2021). "Likewise, mRNA transcript levels of BNP and α-skeletal actin, which are typical markers of cardiac hypertrophy activated by HDAC1/2 that are regulated via REST/mSin3A, were significantly lower in db hearts independent of exercise." (PMID 23835259, 2013). "In summary, HDACs, especially those from class I such as HDAC1, HDAC2, and HDAC8, are key players in the promotion of cardiac hypertrophy through the activation of prohypertrophic signalling pathways and the repression of protective genes." (PMID 40660005, 2025). "The Yi–Xin–Shu (YXS) capsule, a drug suggested by traditional Chinese medicine (TCM), is commonly applied in the treatment of cardiac hypertrophy by regulating the expression of GATA4, HDAC1, and retinoblastoma (RB) and the corresponding signalling pathway." (PMID 40660005, 2025). "For example, SK-7041, a highly selective inhibitor of HDAC1 and HDAC2, alleviated cardiac hypertrophy in the rat TAC model." (PMID 35126818, 2022). "Generally, PI16 is a HDAC1 regulator specifically in CFs, and PI16 overexpression prevents cardiac hypertrophy and fibrosis by inhibiting stress‐induced CF activation." (PMID 32227584, 2020). "YXS inhibits the abnormally high expression of GATA4 in cardiovascular hypertrophy, which can be regulated by interactions between HDAC1 and the general control nonrepressed 5 protein (GCN5)." (PMID 40660005, 2025). "Quisinostat, an HDAC1 inhibitor, show promise in relieving CAMKII-induced cardiac hypertrophy." (PMID 40660005, 2025).
Cognitive impairment (13 papers, 2018 to 2025). Abnormal cognition is characterized by deficits in thinking, reasoning, or remembering. "Histone deacetylase 1 (HDAC1)-deficient mice display age-associated DNA damage accumulation and cognitive impairment." (PMID 34381040, 2021). "HDAC1-deficient mice display age-associated DNA damage accumulation and cognitive impairment." (PMID 32424276, 2020). "Given that HDAC1 was depleted in both neurons and astrocytes in Hdac1 cKO mice, we next assessed whether knockdown of HDAC1 in neurons was sufficient to cause cognitive deficits in aged animals." (PMID 32424276, 2020). "HDAC1 deficiency is directly related to DNA damage accumulation and cognitive impairment in aged wild-type mice, with a similar reduced HDAC1 activity and downregulation observed in the AD mouse model (5XFAD)." (PMID 37627623, 2023). "The interaction of TET2 and histone deacetylase 1 (HDAC1) is involved in regulation of 5hmC levels and expression of the downstream genes associated with AD pathology and cognitive deficits." (PMID 35852137, 2022). "Among the factors examined, histone deacetylase 1 (HDAC1) expression is minimal in both Alzheimer patients and normally aging adults, and HDAC1-deficient mice accumulate age-associated DNA damage and cognitive impairment." (PMID 40725452, 2025). "Furthermore, this study showed that the HDAC inhibitor SAHA alleviated axonal injury and cognitive impairment in rats with SAH by elevating TDP-43 degradation by enhancing the acetylation of HSP70 by inhibiting HDAC1 enzymatic activity." (PMID 35501375, 2022). "Further studies of mouse models have shown that overexpression of HDAC1 in the prefrontal cortex leads to cognitive impairments such as severe impairment of working memory, increased repetitive behaviors, and abnormal motor response profiles in novel environments." (PMID 36406755, 2022). "In conclusion, SAHA alleviated axonal damage and cognitive impairment by mediating the degradation of TDP-43 through the acetylation of HSP70 and the inhibition of HDAC1." (PMID 35501375, 2022). "Furthermore, pharmacological activation of HDAC1 stimulated OGG1 activity, reduces 8-oxoG lesions in aged wild-type and 5XFAD mice, and alleviates 5XFAD cognitive deficits." (PMID 32424276, 2020). "Unlike HDAC1, PET neuroimaging and other postmortem studies have confirmed that the expression of HDAC2 is decreased in the dorsolateral prefrontal cortex of SCZ patients, which may be associated with cognitive impairment." (PMID 36406755, 2022).
atherosclerosis (12 papers, 2016 to 2025). A disease characterized by the build-up of fatty material and calcium deposition in the arterial wall resulting in partial or complete occlusion of the arterial lumen. "Thus, we examined whether HDAC1 expression was also reduced in the atherosclerosis-associated VC models." (PMID 26832969, 2016). "Nan and colleagues identified miR-410 as a microRNA that targets HDAC1 in patients with atherosclerosis." (PMID 40660005, 2025). "Studies have shown that Hcy-induced atherosclerosis is mediated by the increased expression of HDAC1, and the upregulation of HDAC1 reduces the level of acetylation of histone H3 at the lys9 (H3K9ac) site, thereby inhibiting the expression of miR-34a." (PMID 40710369, 2025). "In summary miR-410 and alkyl-glycerophosphate (AGP) play a role in atherosclerosis by downregulating HDAC1 and HDAC2, leading to increased inflammation and endothelial dysfunction." (PMID 40660005, 2025). "Previous studies have found that HDAC1/2 promotes arterial endothelial cell surface vascular cell adhesion molecule-1 expression and atherosclerosis through inhibition of STAT3 acetylation-dependent GATA6 promoter methylation." (PMID 38444939, 2024). "Although there is more evidence that HDAC1 plays a protective role in atherosclerosis and CAD, there is still evidence supporting HDAC1 as an adverse factor in atherosclerosis." (PMID 37405052, 2023). "HDAC1 has a protective role in models of atherosclerosis and is able to mediate the effects of external and ambient stimuli by modulating key endothelial functions such as angiogenesis, inflammatory signaling, redox homeostasis and nitric oxide signaling." (PMID 37405052, 2023). "The inflammation-preventing property of Romidepsin observed in both human and mouse arterial EC motivated us to investigate the potential effect of HDAC1/2 inhibition on the development of diet-induced atherosclerosis in Apoe-/- mice." (PMID 33859766, 2021). "In summary, we provide preclinical evidence that HDAC1/2 contribute to EC activation promoting atherosclerosis, and we reveal a novel epigenetic mechanism by which HDAC1/2 inhibition attenuates this inflammatory response." (PMID 33859766, 2021). "This study identified HDAC1/2 as the specific targets of Romidepsin in suppressing EC activation and atherosclerosis." (PMID 33859766, 2021). "HDAC1 can enhance the expression of miR-224-3p and inhibit atherosclerosis, but it can also inhibit the expression of miR-34a and promote the development of atherosclerosis." (PMID 40710369, 2025). "HDAC1–3, 6, 9, and 11 participate in lipid cell formation, oxidative stress and endothelial cell injury through multiple signalling pathways, contributing to the pathogenesis of atherosclerosis." (PMID 40497340, 2025). "This study investigated whether and how the clinically available histone deacetylases 1 and 2 (HDAC1/2) inhibitor drug Romidepsin epigenetically modulates VCAM-1 expression to suppress atherosclerosis." (PMID 33859766, 2021). "In contrast, HDAC1 has been shown to mediate homocysteine-induced atherosclerosis by reducing the acetylation level of histone H3 at lysine 9 (H3K9ac), leading to the accumulation of total cholesterol (TC), free cholesterol, and triglycerides and accelerating the progression of atherosclerosis." (PMID 41403695, 2025). "The overexpression of HDAC1 enhances the inhibitory effect of miR-224-3p on FOSL2 and inhibits the progression of atherosclerosis by deacetylating HIF-1." (PMID 41403695, 2025). "Moreover, this increase might be attributed to neuroinflammation, as lncRNA-H19 is a significant controller in the progression of atherosclerosis, which can lead to CIS as it causes neuroinflammation by influencing histone deacetylase 1-dependent M1 microglial polarization." (PMID 38255915, 2024). "It has also been proposed that HDAC1 inhibits miR-182-5p and activates the AKT pathway by improving VAV3, thereby promoting the progression of atherosclerosis." (PMID 37405052, 2023).
atherosclerosis (continued). "Although the beneficial and detrimental effects of HDAC1 in atherosclerosis and CAD remain controversial, the important value of HDAC1 in atherosclerosis and CAD cannot be denied." (PMID 37405052, 2023). "It has been noted that HDAC1 can be involved in VCAM-1 expression and promotion of atherosclerosis through inhibition of STAT3 acetylation-dependent methylation of the GATA6 promoter." (PMID 37405052, 2023). "Studies have suggested that blocking miR-410 promotes HDAC1 expression, increases KLF5-mediated IKBα expression, and inhibits the NF-κB pathway, thereby inhibiting the development of atherosclerosis." (PMID 37405052, 2023). "Thus, we investigated whether HDAC1 was also reduced in atherosclerosis-associated calcification without administration of VD3 or calcium." (PMID 26832969, 2016). "The anti-atherosclerotic effect of HDAC1 may be related to the miR-410/HDAC1/KLF5/IKBα/NF-κB axis, with miR-410 playing a potential role in the pathogenesis of atherosclerosis." (PMID 37405052, 2023). "As a more specific HDAC1/2 inhibitor, Romidepsin may hold advantage over SAHA for the intervention of atherosclerosis and other vascular inflammatory disorders." (PMID 33859766, 2021).
colitis (11 papers, 2013 to 2025). Inflammation of the colon. "Butyrate can act directly on intestinal macrophages to reduce inflammatory cytokine production and can ameliorate colitis by maintaining Treg/Th17 balance, inhibiting histone deacetylase 1 and maintaining epithelial barrier integrity." (PMID 34589596, 2021). "Accordingly, IEC-specific Hdac1/2 knockout mice suffer considerably aggravated symptoms when subjected to DSS-induced colitis." (PMID 33842512, 2021). "Indeed, symptoms of intestinal inflammation in a DSS-colitis model can also be alleviated with more specific inhibitors, such as MS-275 (Entinostat) that inhibits mainly HDAC1 and HDAC3 activity." (PMID 33842512, 2021). "In addition, butyrate supplementation inhibits histone deacetylase 1 (HDAC1), leading to downregulation of the inflammatory pathway in rodents with colitis." (PMID 31044315, 2019). "The production of butyrate, an inhibitor of HDAC class I, by polyphenolic derivatives can reduce HDAC1 activity, upregulate AMPK and LC3, and mitigate inflammation in DSS-induced colitis." (PMID 36077368, 2022). "Interestingly, two novel studies have shown that butyrate is able to ameliorate rheumatoid arthritis and colitis by targeting HDAC8 and HDAC1 in Th17 cells, respectively." (PMID 30770822, 2019). "In experimental colitis models, butyrate, a SCFA, produced by F. prausnitzii maintained Th17/Treg balance and exerted significant anti-inflammatory effects via inhibition of the IL-6/signal transducer, the STAT3/IL-17 pathway and promoted Foxp3 expression by targeting histone deacetylase 1 (HDAC1)." (PMID 32429359, 2020).
diabetes (11 papers, 2013 to 2025). "We show that exercise increases total protein O-GlcNAcylation in the type 2 diabetic db+/db+ mouse heart, and that exercise and diabetes have reciprocal effects on the association of HDAC1 and HDAC2 with fetal gene-regulating transcription factors." (PMID 23835259, 2013). "We hypothesized that O-GlcNAc and OGT would physically associate with mSin3A/HDAC1/2 in the heart, and that this interaction would be altered by diabetes and exercise." (PMID 23835259, 2013). "Finally, we found that diabetes and exercise reciprocally affected the physical associations of mSin3A/HDAC1/2." (PMID 23835259, 2013). "Further studies utilizing HDAC1 KO mice with diabetes phenotype will be required to establish the conclusive role of HDAC1 is diabetes induced EPC dysfunctions." (PMID 35673580, 2022). "Multiple of the top DMPs were annotated to genes with relevant functions for diabetes including SREBF1, associated with obesity, type 2 diabetes and insulin sensitivity; ABCG1, involved in cholesterol and phospholipids transport; and HDAC1, of the HDAC family." (PMID 36529747, 2022). "In summary, our findings suggest that vaccarin alleviates endothelial inflammatory injury in diabetes by mediating miR-570-3p/HDAC1 pathway." (PMID 36120375, 2022). "In order to verify whether ESR1, EP300, NFKB1, and HDAC1 are relevant in ginsenoside treatment of diabetes, Western blot analysis was performed on pancreatic tissue from STZ-induced T1DM mice treated with AD-1." (PMID 40508108, 2025). "However, since these interactions have not been studied in the heart, the secondary purpose of this study was to characterize the effects of diabetes and moderate exercise on the mSin3A/HDAC1/2 complex." (PMID 23835259, 2013). "In addition to the use of HDAC inhibitors, direct targeting of HDAC1 may offer further potential for the treatment of diabetes and its complications." (PMID 40508108, 2025). "Moreover, we verified the therapeutic effect of the ginsenoside derivative AD-1 in STZ-induced T1DM mice and observed downregulation of key target proteins (e.g., NFKB1 and HDAC1) in the mouse pancreas, thus providing a basis for innovative applications of ginsenosides in the treatment of diabetes." (PMID 40508108, 2025). "NR4A1 recruits TGF-β target genes, SIN3A, and histone deacetylase 1 (HDAC1) to form a repressor complex, countering the TGF-β-mediated pro-fibrotic effects in diabetes." (PMID 39114353, 2024). "We found that diabetes enhanced the MCAO-induced elevation of NRSF in the hippocampus in accompany with an elevation of its corepressors, HDAC1, and mSin3A, and decrease of β-TrCP." (PMID 35645950, 2022). "The effects of exercise observed in this study were generally modest, which suggests that a moderate level of exercise, such as that prescribed for human patients with diabetes, does not have extreme effects on the mSin3A/HDAC1/2 complex." (PMID 23835259, 2013). "However, the therapeutic effect of ginsenosides on diabetes through HDAC1 has not been proven, and further research is needed." (PMID 40508108, 2025).